SMC4 (structural maintenance of chromosomes 4)
Diseases named in the same sentence as SMC4 in open-access papers (continued):
Sharing a sentence is not in itself a finding about the gene and the disease.
glioma (continued). "In glioma, SMC4 overexpression promotes aggressive phenotypes by TGFβ/Smad signaling." (PMID 36551712, 2022). "In the SMC4 depleted glioma cells, the DNA damage foci increased significantly." (PMID 35992200, 2022). "While it seems a long way to find a promising approach for LGG patients, we believe SMC4 could be a target for the treatment of glioma patients." (PMID 34868977, 2021). "We observed the elevated SMC4 in the MYB overexpressed glioma cells." (PMID 34868977, 2021). "In addition to being found as a prognostic marker for gliomas in this article, structural maintenance of chromosomes 4 (SMC4) has also been found to be a survival marker for colorectal cancer, breast cancer, and prostate cancer." (PMID 34295296, 2021). "There are three major histological subtypes of glioma (astrocytoma, oligoastrocytoma and oligodendroglioma) and SMC4 overexpression correlated with the reduced OS in astrocytoma and oligodendroglioma and correlated with reduced PFI in astrocytoma and oligo-astrocytoma." (PMID 34868977, 2021). "Further survival analysis revealed that elevated SMC4 correlated with poor prognosis of patients with glioma, indicating that SMC4 may serve as a valuable prognostic factor in glioma." (PMID 28287612, 2017). "Moreover, the transforming growth factor β (TGFβ)/Smad signaling pathway, which was activated in SMC4-transduced glioma cells and inhibited in SMC4-silenced glioma cells, contributed to SMC4-mediated glioma cell aggressiveness." (PMID 28287612, 2017). "Consistently, the expression of phosphorylated Smad3 was higher in the SMC4-overexpressing glioma tissues and lower in the SMC4-silenced tissues compared with control tumor tissues, respectively, which further support the notion that SMC4 contributes to activation of TGFβ/Smad signaling." (PMID 28287612, 2017). "Our results provide new insight into the oncofunction of SMC4 and the mechanism by which the TGFβ/Smad pathway is hyperactivated in gliomas, indicating that SMC4 is a valuable prognostic factor and a potential therapeutic target in gliomas." (PMID 28287612, 2017). "Next, we determined whether SMC4 protein upregulation correlated with poor prognosis of glioma as the disease progressed." (PMID 28287612, 2017). "SMC4 overexpression markedly promoted glioma cell migration and invasive capability in vitro, as well as tumorigenicity in vivo, which was involved in alteration of expression of the invasion-related gene MMP2, MMP9 and the proliferation marker Ki67, but SMC4 downregulation reduced it." (PMID 28287612, 2017). "In addition, SMC4 upregulation in glioma cells drastically increased their proliferative capability by accelerating G1–S-phase transition." (PMID 28287612, 2017). "Similarly, the effect of SMC4 on the invasive capability of glioma cells was confirmed using the LN18 and U118MG cell lines via Transwell assay." (PMID 28287612, 2017). "The results provide new insight into the oncofunction of SMC4 and the mechanisms by which the TGFβ/Smad pathway is hyperactivated in gliomas, indicating that SMC4 is a valuable prognostic factor and potential target in glioma drug therapy." (PMID 28287612, 2017). "Therefore, we investigated the roles played by SMC4 in the proliferative and migration capability of glioma cells." (PMID 28287612, 2017). "Kaplan–Meier analysis and log-rank testing revealed that SMC4 protein expression levels in glioma specimens were inversely correlated with survival time, whether at WHO grades I–II or at WHO grades III–IV." (PMID 28287612, 2017). "Moreover, the TGFβ/Smad pathway was hyperactivated and contributed to SMC4-mediated glioma cell aggressiveness." (PMID 28287612, 2017). "The effect of SMC4 on glioma cell proliferation was confirmed in the LN18 and U118MG cell lines." (PMID 28287612, 2017).
glioma (continued). "As TGFβ/Smad pathways are central mediators of signals from the receptors for TGFβ superfamily members to the nucleus, we first assessed the effect of SMC4 modulation on Smad transcriptional activity in glioma cells by using a Smad reporter luciferase activity assay." (PMID 28287612, 2017). "SMC4 mRNA expression correlated positively with both early TGFβ-activated and delayed TGFβ-induced gene signatures, suggesting that SMC4 promotes glioma cell aggressiveness and activates the TGFβ signaling pathway." (PMID 28287612, 2017). "Moreover, univariate and multivariate survival analyses revealed that SMC4 expression was an independent prognostic factor of glioma (P<0.001) similar to the WHO grade (P<0.001)." (PMID 28287612, 2017). "However, we couldn’t observe an increased sensitivity to temozolomide (TMZ) in SMC4 depleted SW1088 cells or LN229 cells Together, we showed SMC4 could facilitate the repair of DNA replication damage in glioma cells." (PMID 34868977, 2021). "The result showed SMC4 and neoplasm histologic grade could simultaneously affect the OS of glioma patients, while SMC4 together with mold/dust allergy history, neoplasm histologic grade and new tumor event after initial treatment could independently affect the PFI of the glioma patients." (PMID 34868977, 2021). "Furthermore, SMC4 protein expression increased markedly with human glioma WHO grade (left)." (PMID 28287612, 2017). "The violin plot demonstrated that IGFBP2, SMC4, PLAT, and ANXA1, showed relatively higher expression levels in pericytes and glioma cells compared to other scoring genes." (PMID 39906742, 2024). "Another study performed in low-grade gliomas reported a consistent signature in the methylation of MGMT, MLH3, RAD21, and SMC4 promoter region predictive value for response to temozolomide." (PMID 35359376, 2022). "Currently, studies have shown that the subunits of condensin, such as NCAPG, SMC4, and NCAPG2, have been reported to be involved in the glioma pathogenesis." (PMID 35992200, 2022). "To confirm the regulation role of E2F1 for SMC4, we performed E2F1 silencing in glioma tumour cells." (PMID 35615996, 2022). "Recently, ABCC3 has been included in gene signatures (ABCC3, CD44, TNFRSF1A, and MGMT24; ABCC3, SMC4, EMP3, WEE1, and HIST1H2BK44) that classify glioma patients in agreement with therapeutic response to chemotherapeutic agents, including TMZ." (PMID 36585418, 2022). "The binding of transcription factors at the SMC4 promoter region is predicted and MYB and E2F1 are identified as potential transcription factors for SMC4 in glioma patients." (PMID 34868977, 2021). "The results showed that combining si-SMC4 with these drugs significantly reduced the invasiveness of LN299 cell lines compared to single-agent treatments, highlighting the role of disulfidptosis-Tex in glioma metastasis." (PMID 39949776, 2025). "Indeed, in our study, we have proved that silencing of SMC4 enhances the sensitivity of TMZ to kill U87 and U373 glioma cells." (PMID 35615996, 2022). "Although SMC4 is not differentially expressed concerning the symptoms, location and first-course response of the glioma patients, SMC4 is overexpressed in patients with recurrence and advanced histologic staging." (PMID 34868977, 2021). "SMC4 mRNA expression was significantly higher in anaplastic astrocytoma and in GBM than in normal brain tissues, which analysis of another 552 human glioma specimens from The Cancer Genome Atlas (TCGA) confirmed." (PMID 28287612, 2017). "Survival analyses showed that high SMC4 mRNA expression was negatively correlated with prognosis in both patients with lower-grade glioma and patients with GBM from TCGA data set, suggesting that the expression of SMC4 mRNA is an indicator of survival in glioma." (PMID 28287612, 2017).
glioma (continued). "Functional studies in U-251MG and LN229 glioma cells including CCK-8, EdU, cell cycle, Transwell, and wound-healing assays were combined with subcutaneous xenograft and tail-vein metastasis mouse models to evaluate SMC4’s effects on proliferation, migration, invasion, and metastasis." (PMID 40933894, 2025). "Furthermore, we confirmed the translation expression level of the hub genes using the HPA database, and the prognostic biomarkers were found to be stained strongly or moderately.: SMC4, OCR1, CDCA8, and DLGAP5, indicating that these hub genes were translated more in glioma samples." (PMID 38926605, 2024). "Similarly, SMC4 has also been shown to dysfunction in PAL, breast cancer, hepatocellular carcinoma (HCC), colorectal cancer (CC), lung adenocarcinoma, prostate cancer and glioma." (PMID 29467813, 2018). "Results showed SMC4 could effectively predict the OS and PFI in glioma patients independent of new tumor event(s) or histologic grade (G2 or G3)." (PMID 34868977, 2021).
colorectal cancer (15 papers, 2014 to 2025). A primary or metastatic malignant neoplasm that affects the colon or rectum. "SMC-4 expression was significantly higher in colorectal cancer and was associated with tumorigenesis." (PMID 31615392, 2019). "It is upregulated in various malignancies, including lung cancer, breast cancer, liver cancer and, in particular, colorectal cancer, with a high SMC4 expression when compared with normal tissue." (PMID 35202347, 2022). "The present study demonstrated that miR-124-5p inhibited the tumorigenesis gene, SMC4, which upregulated the expression of miR-124-5p, thereby improving the OS of colorectal cancer patients." (PMID 25081869, 2014). "Thirdly, SMC4 also shows dysregulations in colorectal cancer cells." (PMID 34557090, 2021). "Therefore low expression levels of microRNA-124-5p and overexpression of SMC4 is correlated with poor prognosis in colorectal cancer." (PMID 34557090, 2021). "Additionally, low expression levels of miR-124-5p correlated with poor prognosis in colorectal cancer via targeting of SMC4." (PMID 32220226, 2020). "Similarly, SMC4 was upregulated in colorectal cancerous tissue and knockdown of SMC4 plays a suppressive role in the proliferation, cell cycle and apoptosis of colorectal cancer cells." (PMID 29467813, 2018).
breast carcinoma (12 papers, 2009 to 2025). "The results of our prognostic analysis in the Kaplan-Meier Plotter database show that the up-regulation of SMC4 expression levels is significantly related to the poor prognosis of patients with sarcoma, breast cancer, liver cancer, or ovarian cancer." (PMID 36719264, 2023). "Based on the CPTAC database, SMC4 protein level was elevated in breast cancer compared with normal samples (p < 0.001)." (PMID 37007153, 2023). "The receiver operating characteristic (ROC) curve indicated that SMC4 expression had good predictive power with an area under the curve (AUC) of 0.855 (95% confidence interval [CI] = 0.831–0.879) to discriminate breast cancer tissues from normal tissues." (PMID 37007153, 2023). "Recent studies have shown that the expression level of SMC4 is abnormally high in liver cancer, breast cancer, and colon cancer." (PMID 33460400, 2020). "3q25, the locus of SMC4 belonging to, had been proved to be involved in high level of recurrent DNA amplifications in breast cancer cell lines." (PMID 31871499, 2019). "In conclusion, we found that mRNA expression of SMC4 was upregulated in invasive breast cancer cells." (PMID 31871499, 2019). "In breast cancer, SMC4 is down-regulated in cell lines that were paclitaxel-resistant but combination synergistic." (PMID 29467813, 2018). "Research also suggests that SMC4 is a potential biomarker of the sensitivity of breast cancer cells to paclitaxel and the response to SAHA/paclitaxel combination treatment." (PMID 24980149, 2014). "Additionally, higher expression of SMC4 was connected to worse outcomes of sarcoma, gastric cancer, breast cancer, liver cancer or ovarian cancer." (PMID 36719264, 2023). "Here, we show that the mRNA expression of SMC4 was upregulated in invasive breast cancer cells." (PMID 31871499, 2019). "SMC4 mRNA level is a good prognostic biomarker for patients with breast cancer." (PMID 31871499, 2019). "Nevertheless, the succinct role of SMC4 in breast cancer and the relationship between SMC4 expression and clinical outcomes remain unknown." (PMID 31871499, 2019). "SMC4 mRNA level was significantly upregulated in breast cancer tissues (P < 0.001)." (PMID 31871499, 2019). "Moreover, subsequent studies confirmed that interference with SMC4 mRNA expression effectively inhibited the proliferation, migration, and invasive ability of breast cancer MDA-MB-231 cells, with the mechanism possibly related to the activation of the PI3K/AKT signaling pathway." (PMID 37007153, 2023). "Similarly, SMC4 functions as a carcinogen and affects the OS of patients with breast cancer." (PMID 35372377, 2022). "Bioinformatics analysis demonstrated that the unpaired (p < 0.001) and paired (p < 0.001) differential expression analyses between normal and breast cancer groups indicated that SMC4 was expressed significantly higher in tumors compared to normal tissue." (PMID 37007153, 2023). "In this study, we analyzed the expression of SMC4 in breast cancer tissues and adjacent noncancerous tissue." (PMID 31871499, 2019). "However, in the prognostic classifier for breast cancer, the weight of the well-studied MCM7 oncogene was essentially lower than the weight of the SMC4 gene with less reported oncogenic potential." (PMID 29402894, 2018). "In patients with nontriple negative breast cancer (non-TNBC), the high SMC4 expression group had poor prognosis (P = 0.001)." (PMID 31871499, 2019). "Subgroup analyses show that in nontriple negative breast cancer (non-TNBC) patients, the high SMC4 mRNA expression, older age (>65), negative progesterone receptor, and advanced stages (III-IV) were independent risk factors (HR = 3.293, 95% CI 1.257-8.625, P = 0.015)." (PMID 31871499, 2019).
liver cancer (12 papers, 2014 to 2025). An epithelial or non-epithelial malignant neoplasm that arises from the liver. "A previous study on SMC4 in liver cancer and lymphoma showed that SMC4 was associated with tumor size and the advanced stages of cancer, however there are no studies examining SMC4 and PCa." (PMID 25093842, 2014). "In addition, SMC4 expression was significantly associated with tumor size, dedifferentiation, advanced stages and vascular invasion of the primary liver cancers." (PMID 31615392, 2019). "Elevated expression of SMC4 was discovered in liver cancer and colon cancer and can promote their growth." (PMID 36719264, 2023). "SMC4 acts as a direct target of miR-219 and can inhibit liver cancer cell proliferation, migration, and invasion." (PMID 34527684, 2021). "Levels of SMC4 protein were significantly associated with tumor size, differentiation, TNM stage, and vascular invasion of primary liver cancer." (PMID 24980149, 2014). "Moreover, SMC4 can promote the growth of liver cancer and colon cancer." (PMID 33460400, 2020).
hepatocellular carcinoma (10 papers, 2014 to 2025). A malignant tumor that arises from hepatocytes. "SMC4 is highly conserved across species and is observed to be overexpressed in multiple solid tumors, including hepatocellular carcinoma, colorectal cancer, and prostate cancer, etc.." (PMID 34868977, 2021). "SMC4 transcription and expression is negatively regulated by miR-219 in human hepatocellular carcinoma 97-H, HepG2 cell lines." (PMID 29467813, 2018).
prostate carcinoma (9 papers, 2014 to 2025). A carcinoma that arises from epithelial cells of the prostate gland. "Structural maintenance of chromosome protein 4 (SMC4) has been implicated in prostate cancer metastasis." (PMID 40278414, 2025). "Although elevated expression of SMC4 is significantly associated with the metastatic cascade and offers a poor prognosis in prostate cancer, its expression and potential role in the pathogenesis of prostate cancer remain obscure." (PMID 40278414, 2025). "In prostate cancer, higher expression of SMC4 is significantly associated with the metastatic cascade." (PMID 29467813, 2018). "SMC4 belongs to a family of genes linked with poor outcome in prostate cancer, and finally, GTSE1 was described as associated with worse prognosis in uterine leimyosarcoma." (PMID 28423514, 2017). "To determine the functional effects of SMC4 on metastatic prostate cancer cells, we inoculated RM1 cells into the tibiae of C57BL/6J mice and then reinjected lung metastatic tumor cells into shin bones of the mice." (PMID 40278414, 2025). "In summary, our findings illuminated the profound influence of SMC4 overexpression on the heightened aggressiveness of prostate cancer cells, specifically in facilitating their metastatic dissemination to distant organs." (PMID 40278414, 2025). "In our study, the expression of SMC4 was increased in a prostate cancer cell line with high lung metastatic specificity (RM1‐LM), an organ‐specific metastatic cell line that we developed." (PMID 40278414, 2025). "While existing evidence indicates a plausible link between SMC4 and oncogenic manifestations, its precise role in the trajectory of prostate cancer remains ambiguous." (PMID 40278414, 2025). "Our investigation uncovered the suppression of mTOR activity and Rheb expression after SMC4 knockdown, suggesting the potential role of SMC4 in governing the growth and metastasis of prostate cancer cells through the Rheb/mTOR signaling pathway." (PMID 40278414, 2025). "IHC results from human prostate cancer tissue microarrays indicated that SMC4 protein expression was elevated in prostate cancer tissues in tandem with increased Gleason grade." (PMID 40278414, 2025). "To elucidate the mechanism responsible for the SMC4 promotion of prostate cancer cell metastasis, we performed RNA‐Seq analysis in RM1‐LM‐Vector and SMC4 knockdown cells." (PMID 40278414, 2025). "SMC4 overexpression also promotes cancer cell aggressiveness and metastasis in human prostate cancer cell lines." (PMID 40278414, 2025). "By bio-molecular investigation about SMC4 in prostate cancer, we should confirm the mechanism of SMC4 in PCa." (PMID 25093842, 2014). "Nevertheless, the contribution of SMC4 to prostate cancer metastasis remains unelucidated." (PMID 40278414, 2025). "This suggested that SMC4 was important in prostate cancer cell metastasis." (PMID 40278414, 2025). "In addition, analyses of GSE21034 and GSE35988 databases revealed that GLUT1 expression was augmented in metastatic prostate cancer in men relative to that in primary prostate cancer, a trend consistent with SMC4 expression." (PMID 40278414, 2025). "Also, SMC4 knockdown dramatically decreased lung metastasis and colonization relative to RM1‐LM‐Vector cells, suggesting that SMC4 promoted prostate cancer metastasis in addition to tumor growth." (PMID 40278414, 2025). "Furthermore, our examination of the Oncomine prostate cancer datasets revealed a noteworthy elevation of SMC4 mRNA expression in metastatic prostate cancer compared to that in primary tumors, suggesting an ongoing contribution to the progression of metastasis." (PMID 40278414, 2025). "Furthermore, we correlated the elevated expression of SMC4 with a commensurately augmented expression of GLUT1 in prostate cancer metastasis, and cellular metabolic assays revealed that SMC4 knockdown suppressed glycolytic rate." (PMID 40278414, 2025). "We measured the expression of SMC4 in human prostate cancer cell lines." (PMID 40278414, 2025).